GRAPL (GRB2 related adaptor protein like)
Synonyms: GRAPLDR
Tractability: PROTAC: ubiquitination databases record sites on it.
Gene: Protein-coding gene on chromosome 17 (19,127,535 to 19,162,274, forward strand). Ensembl gene ENSG00000189152.
Subcellular location (Human Protein Atlas): Centrosome
Gene Ontology:
Molecular function: protein binding; receptor tyrosine kinase binding; signaling adaptor activity
Biological process: cell migration; enzyme-linked receptor protein signaling pathway
Cellular component: cytoplasm; cytosol
Homologues: Orthologues: macaque GRAP (89% identical), dog GRAP (87% identical), mouse Grap (86% identical), rat Grap (84% identical), tropical clawed frog grap (65% identical), zebrafish grapa (57% identical), zebrafish grapb (57% identical), Caenorhabditis elegans nck-1 (37% identical), Drosophila melanogaster dock (33% identical). Paralogues in human: GRAP (87% identical), GRB2 (57% identical), GRAP2 (42% identical), NCK2 (39% identical), NCK1 (38% identical), SLA2 (31% identical), SLA (25% identical), SH2D5 (23% identical), DAPP1 (18% identical).
Diseases named in the same sentence as GRAPL in open-access papers:
GRAPL is named in the same sentence as 2 diseases in open-access papers, as found by Europe PMC text mining. Sharing a sentence is not in itself a finding about the gene and the disease.
GRAPL shares sentences with these, for which no sentence is quoted: lung carcinoma (1 paper); tumor (1).